TLR8 (toll like receptor 8)
Diseases named in the same sentence as TLR8 in open-access papers (continued):
Sharing a sentence is not in itself a finding about the gene and the disease.
Autoimmunity (continued). "For example, evidence for a direct link between gene escape and female-biased autoimmunity has been demonstrated for TLR7 and TLR8, with their higher escape gene dose leading to enhanced immune responses." (PMID 40312568, 2025). "Uncontrolled TLR7, TLR8, or TLR9 activation can lead to responses to self-nucleic acids and autoimmunity." (PMID 38780621, 2024). "The mechanism behind the development of autoimmunity was found to be reduced ability of TLR8 to regulate TLR7 signaling, as well as increased binding of TLR8 to TLR7 ligands, which increased TLR7 signaling." (PMID 38791389, 2024). "Numerous studies have implicated TLR7 as the main driver of SLE disease, while both TLR8 and TLR9 have been shown to have more regulatory roles where they contribute to dampening TLR7 signaling and thereby prevent autoimmunity." (PMID 38791389, 2024). "Intracellular TLRs recognise bacterial and viral nucleic acids and self-nucleic acids in autoimmunity; these include TLR3, TLR7, TLR8, TLR11, and TLR12." (PMID 37761018, 2023). "We will briefly introduce nucleic acid TLRs and present data for the interplay of TLR7 with TLR8 and TLR9 and its importance in autoimmunity." (PMID 36389822, 2022). "The importance of this regulation is reflected by the fact that deletion of TLR8 or/and TLR9 in mice or even diminution of TLR8 expression in humans, leads to increased TLR7 signaling and subsequent autoimmunity." (PMID 36389822, 2022). "Nevertheless, by now it is undoubtedly documented that TLR7 plays a central role in SLE, where both TLR8 and TLR9 restrain TLR7 signaling and thus, can protect from autoimmunity." (PMID 36389822, 2022). "Cells from Tlr8-/- mice showed increased expression of Tlr7 and were hyperresponsive to various TLR7 ligands, resulting in the animals developing spontaneous autoimmunity." (PMID 33597952, 2020). "Therefore, both TLR8 and TLR9 are able to restrain TLR7 and their deletion leads to autoimmunity due to increased TLR7 responses." (PMID 36389822, 2022). "Murine TLR8 is functional and mice deficient in TLR8 have increased TLR7 signaling due to the lack of inhibition by TLR8, and DCs produce high amounts of cytokines causing spontaneous autoimmunity, autoantibodies, splenomegaly, and reduced B cell numbers." (PMID 34199501, 2021). "Thus, TLR7 and TLR8, due to their localization on the X chromosome, might be overexpressed in females and could make them prone to type I IFN–driven inflammation and autoimmunity." (PMID 36633910, 2023). "However, UNC93B1 upregulation may also increase the responsiveness of TLR3, TLR7, TLR8, and TLR9 to their agonists, and conditions that lead to increased UNC93B1 expression may yield autoimmune disorders." (PMID 33597952, 2020). "Nevertheless, a study of TLR8−/− mice indicated that TLR8 regulates TLR7 expression and protects mice from autoimmunity, since TLR8−/− mice, but not TLR8−/− TLR7−/− mice, developed features of lupus-like syndrome." (PMID 30619338, 2018). "In the skin of SSc patients, the infiltration and activation of plasmacytoid dendritic cells (pDCs) via PI3Kδ pathway leads to aberrant expression of TLR8 (otherwise not expressed in pDCs) that induces CXCL4, IFN-α, IL6, and TNF secretion contributing to skin fibrosis and autoimmunity." (PMID 32210969, 2020). "Therefore, the evidence indicates that murine TLR7 and TLR8 possess unique functions in regulating autoimmunity and neuronal morphology, and although there is crosstalk between TLR7 and TLR8, they are not functionally redundant." (PMID 31684953, 2019).
psoriasis (27 papers, 2013 to 2025). An autoimmune condition characterized by red, well-delineated plaques with silvery scales that are usually on the extensor surfaces and scalp. "Since the topical application of imiquimod, a ligand of TLR7 and TLR8, has been shown to causes a psoriasis-like pathology in mouse skin through the activation of dermal DCs and Langerhans cells, we expect β-damascone to ameliorate psoriasis, even from the viewpoint of modifications to DC functions." (PMID 36845043, 2023). "Topical application of IMQ, a ligand of Toll-like receptor 7 (TLR7) and TLR8, to the skin induces psoriasis-like manifestations in mice, where γδT cells are associated with disease development." (PMID 38348035, 2024). "TLR signaling is a key trigger of NETs formation and, in fact, NETs formation by TLR8 activation has been identified as part of a self-potentiating inflammatory loop that drives chronic inflammation in psoriasis." (PMID 35261923, 2022). "IMQ, which serves as a ligand for TLR7 and TLR8 and as an effective immune activator, can be topically used to induce psoriasis-like skin lesions in a mouse model." (PMID 35153762, 2021). "It is well known that IMQ is a ligand of Toll-like receptor 7 (and TLR8 in humans) and recapitulates some of the immunological events in psoriasis patients." (PMID 33990689, 2021). "Topical application of IMQ, an effective agonist of TLR7 in mice (TLR7 and TLR8 in humans), can induce and exacerbate psoriasis by activating the IL-23/Th17 pathway via TLR724,25." (PMID 32873845, 2020). "Topical application of imiquimod, a ligand of TLR7 and TLR8, induces a psoriasis-like skin inflammation with typical microscopic and macroscopic psoriatic markers in mice, and is the most commonly used psoriasis animal model." (PMID 32106600, 2020). "Recently, activation of human dendritic cells through TLR7 and TLR8 by self RNA-antimicrobial peptide complexes provided new insights into the mechanism that provokes the auto-inflammatory responses in psoriasis." (PMID 24146965, 2013). "In turn, NET-associated RNA (naRNA), along with the antimicrobial peptide LL37 that induces platelet aggregation and promotes thrombus formation, triggers cytokine and NET release by PMNs through Toll-like receptor 8 (TLR8) signaling and aggravates inflammation in psoriasis and CVD." (PMID 37654493, 2023). "The responsiveness to TLR7 and TLR8 stimulation is relevant for the activation of slanMo in autoimmune diseases and psoriasis where single stranded RNA motives are either contained within autoimmune complexes or being complexed by the antimicrobial peptide LL37 as in psoriasis." (PMID 31191513, 2019). "IMQ is a ligand for Toll like receptors (TLR7 and TLR8) and when topically applied produces psoriasis-like skin lesions in mice which display many of the same characteristics as those observed in psoriasis in humans; elevations of IL-23/IL-17 and the dependency upon IL-22 to develop the lesions." (PMID 25965695, 2015). "Indeed, the use of the TLR7 and TLR8 agonist imiquimod in patients with cancer exacerbates psoriasis." (PMID 23593527, 2013). "In contrast, TLR8 is expressed mainly by mDCs, which are the dominant cell population in psoriasis lesions, and where activation of this TLR would be predicted to activate NFkB responsive pathways, which may include IL-23 production from DCs." (PMID 24386404, 2013). "Thus, AKBA might have an anti-inflammatory effect on psoriasis by inhibiting the maturation and activation of DCs via the TLR8 and IRF signaling pathways." (PMID 32671018, 2020). "Thus, the protein expression levels of TLR7 and TLR8 in IMQ-induced psoriasis mice were detected." (PMID 31181689, 2019). "Effects of IMQ are mostly mediated by the activation of TLR7 and TLR8 expressed on the immune cells, whereas mannan was shown to activate mannose receptor (CD206) on macrophages in psoriasis, psoriatic arthritis, and rheumatoid arthritis-like disease models." (PMID 36645209, 2023).
psoriasis (continued). "For example, paeonol inhibits the maturation and activation of DCs by reducing MyD88 and TLR8 proteins in the TLR7/8 signalling pathway, and ultimately alleviates psoriasis-like skin lesions in BALB/c mice." (PMID 35095512, 2021). "TLR-8 and TLR-9 antagonists, tested in an IL23 psoriasis mouse model, inhibited the Th1 and Th17 responses, and were active against psoriasis in a proof-of-concept trial." (PMID 28095445, 2017). "Interestingly, Datura metel L.—a traditional Chinese medicine known to suppress the progression of IMQ‐induced psoriasis in a the mouse model—can suppress TLR7 and TLR8 expression and inhibit the activity of the TLR7/8‐MyD88‐NF‐κB‐NLRP3 inflammasome pathway." (PMID 34936223, 2022). "Recent studies have found that certain factors regulate the AIM2 inflammasome signaling pathway and participate in the pathogenesis of psoriasis, including prokineticin 2 (PK2), caspase recruitment domain family member 18 (CARD18), aurora kinase A (AURKA), TLR-7, TLR-8, and TLR-9 antagonists." (PMID 36118867, 2022). "Psoriasis is a chronic inflammatory autoimmune disease that can be initiated by excessive activation of endosomal toll-like receptors (TLRs), particularly TLR7, TLR8, and TLR9." (PMID 28894754, 2017). "Our present study showed that the protein expression levels of TLR7, TLR8, MyD88, and p-NF-κB in the skin of mice induced by IMQ were upregulated significantly; consequently, TLR7/8–MyD88–NF-κB signaling was considered to play a critical role in IMQ-induced psoriasis." (PMID 31181689, 2019).
lung carcinoma (23 papers, 2016 to 2025). "Further, if the sRNA_1096 acts as a ligand to TLR8 similar tomir-21, upon remittance to the host, it may activate TLR8pathway and along with increasing risk it may also regulatechemoresistance in lung cancer individually or incombination with mir-21." (PMID 30237679, 2018). "The expression level of TLR8 increases in lung cancer cells, and TLR8 is one of the factors contributing to poor prognosis of lung cancer." (PMID 40727252, 2025). "Engagements of TLR7 or TLR8 agonists in lung cancer cells can induce the activation of NF-κB and upregulation of Bcl-2 expression, leading to increases in cell survival and resistance to apoptosis." (PMID 37443143, 2023). "Both TLR7 and TLR8 stimulation activate the NF-κB pathway, thought to improve cell survival, inflammation, and chemoresistance in primary lung cancer cells." (PMID 36389785, 2022). "As a single-stranded RNA sensor, the activation of TLR8 can also promote the survival and chemoresistance of lung cancer cells." (PMID 35923697, 2022). "Previous studies have reported that the expression IGF2BP1, TLR8, PIWIL4, and GAPDH were associated with tumorigenesis and progression of lung cancer patients, which consistent with our results." (PMID 32087603, 2020). "EV-miR-21 and miR-29a from lung cancer cells induce NF-κB activation and the release of prometastatic inflammatory cytokines in murine and human macrophages by activating TLR7 and TLR8 respectively, which promotes lung cancer metastasis." (PMID 32503543, 2020). "The microRNA miR21 (released from lung cancer cells) has recently been shown to bind to TLR8, leading to NF-κB-mediated up-regulation of inflammatory cytokines." (PMID 32595650, 2020). "Triggering of TLR7 and TLR8 expressed by human lung cancer cells induced cell survival and chemo-resistance." (PMID 29568370, 2018). "In vitro, TLR8 agonist stimulation of lung cancer cells resulted in the activation of NF‐κB, increased expression of proinflammatory factors (IL‐6, IL‐8, GM‐CSF, IL‐1α, and IL‐12), and increased expression of antiapoptotic proteins Bcl‐2, VEGFR2, and chemokine receptors." (PMID 39003635, 2024). "TLR8, as members of the TLR family, are highly expressed in lung cancer tissues and play a role in chronic inflammation, tumor formation, and metastasis." (PMID 39003635, 2024). "The expressions of EMR3, NCF1, CSF2RB, DYSF, TLR8, and HCK in the lung cancer group were significantly different from those of the control group." (PMID 35923697, 2022). "ZEB1, TRAF4, and TGF-β1 are involved in lung cancer metastasis by EMT proteins while PD-L1, EGFR, TLR7 and TLR8 are involved in inhibiting the immune system." (PMID 36032679, 2022). "Exosomal miR-21 and miR-29a from lung cancer cells activate mouse TLR7- and human TLR8-mediated NF-κB activation in immune cells and the production of proinflammatory IL-6 and TNF-α to promote lung cancer and metastasis in mice." (PMID 35562884, 2022). "For example, lung cancer cells activate Toll‐like receptors TLR7 and TLR8 on immune cells via exosomal miR‐21 and miR‐29a, leading to tumour growth and metastasis." (PMID 32391938, 2020). "In lung cancer, TLR7 and TLR8 signaling promoted cell proliferation and chemoresistance and was associated with the poor survival of patients." (PMID 27248820, 2016). "We incubated HEK-Blue cells expressing human TLR2, TLR3, TLR4, TLR5, TLR7, TLR8, TLR9, or the intracellular PRR protein NOD2 with 100 μg/ml DRibbles derived from the mycoplasma free lung cancer cell line UbiLT3." (PMID 27490927, 2016). "However, the antibody staining level of TLR8, PIWIL4, and ZC3H12C were relatively reduced in lung cancer tissue." (PMID 32087603, 2020). "For example exosomes derived from lung cancer cells transferred miR‐21/29a to activate TLR7 and TLR8 on immune cells, which may contribute to tumour growth and metastasis." (PMID 32391938, 2020).
lung carcinoma (continued). "The sRNA_1096 may be transported tohost and predisposed during M. tuberculosis infection and lateracts as ligand to TLR8 through its GTTG/ GUUG sequencesimilar to mir-21 to activate TLR8 mediated prometastaticpathways and chemoresistance in lung cancer." (PMID 30237679, 2018).
asthma (19 papers, 2010 to 2025). "Specifically, polymorphisms in both TLR7 and TLR8 were associated with eosinophil count, serum IgE levels, lung function, and asthma severity." (PMID 40672946, 2025). "The association between rs3764880 of TLR8 and tuberculosis susceptibility in males has been confirmed in European, Russian, and Chinese populations and other SNPs of TLR8 were associated with asthma, SLE, and chikungunya virus infection." (PMID 33763088, 2021). "Association of TLR8 have been also reported for pulmonary tuberculosis, asthma and related atopic disorders." (PMID 29871630, 2018). "Recently, SNPs of both TLR7 & TLR8 have been identified and found to be associated with asthma, rhinitis and atopic dermatitis." (PMID 24819048, 2014). "For TLR8, association with asthma phenotype in childhood was shown for rs2407992 separately, and rs5741883, rs3764879, rs3764880, rs5744077, rs2159377, and rs2407992 haplotypes, but not rs3761624." (PMID 23496969, 2013). "Genetic studies have also linked TLR7 and TLR8 polymorphisms to increased risk of asthma." (PMID 26477783, 2016). "Regarding asthma, TLR2, TLR4, TLR7, TLR8, and TLR9 polymorphisms have been elucidated by their implication in allergic and asthma pathways and are also related to allergic and asthma exacerbations." (PMID 37920579, 2023). "For example TLR7 and TLR8 are associated with human asthma while ligands of TLR7 and TLR8 can prevent airway remodeling caused by experimentally induced asthma." (PMID 21108806, 2010). "Estrogen can activate immune genes such as TLR7/TLR8 on the X chromosome, enhance eosinophil infiltration, and promote IL-13-mediated mucus secretion, making female asthma patients more prone to hormone-dependent acute exacerbations (e.g., during menstrual periods or perimenopause)." (PMID 41244254, 2025). "This suggests that genetic variations in TLR7 and TLR8 may indeed contribute to asthma pathogenesis, particularly influencing disease characteristics rather than initial susceptibility." (PMID 40672946, 2025). "We evaluated whether post-bronchiolitis asthma was associated with polymorphisms in the TLR3 rs3775291, TLR4 rs4986790, TLR7 rs179008, TLR8 rs2407992, TLR9 rs187084, and TLR10 rs4129009 genes." (PMID 28592890, 2017). "Intracellular TLRs agonists such as TLR7/TLR8 agonists have also been evaluated in asthma." (PMID 27274620, 2016). "Furthermore, we found that the expression of some molecules such as CD14, TLR5, TLR6, TLR8, TREM-1, but also IRAK-1 and IRAK-2 genes was significantly negatively associated with total serum IgE, atopic sensitization, or asthma." (PMID 24603716, 2014). "The present study was carried out to complement this exploratory study series by evaluating whether the TLR3 rs3775291, TLR4 rs4986790, TLR7 rs179008, TLR8 rs2407992, TLR9 rs187084, and TLR10 rs4129009 polymorphisms are associated with post-bronchiolitis asthma." (PMID 28592890, 2017). "Resiquimod is a typical TLR7/TLR8 agonist and in vivo suppresses AHR as well as airway remodeling in asthma." (PMID 27274620, 2016). "In addition, ISS from asthma patients also had an activation effect on TLR3, TLR7, and TLR8, which play crucial roles in immune regulation." (PMID 39950864, 2025).
tuberculosis (17 papers, 2012 to 2025). A chronic, recurrent infection caused by the bacterium Mycobacterium tuberculosis. "In particular, the only high frequency missense polymorphism in the TLR8 gene (rs3764880) has been implicated in a number of diseases, such as tuberculosis and progression of HIV infection." (PMID 22857391, 2012). "Interactions between dsRNA and TLR-8 result in caspase-8 activity and TLR-8 polymorphisms are associated with increased susceptibility to tuberculosis." (PMID 22253841, 2012). "Furthermore, polymorphisms in the TLR8 gene on the X chromosome, which is associated with tuberculosis susceptibility, is linked to boys." (PMID 40558589, 2025). "TLR8 signaling may, therefore, both regulate susceptibility to tuberculosis and provide novel drug targets." (PMID 40338743, 2025). "The SNP rs3764880 on TLR8 has been associated to tuberculosis." (PMID 29871630, 2018). "Different single nucleotide polymorphisms of TLR8 and TLR9 confer varying degrees of risk in the development of tuberculosis, suggesting that TLR8 and TLR9 are involved in tuberculosis." (PMID 35309296, 2022). "Interestingly, similar results were found in which the relative mRNA expression levels of TLR2, TLR4, and TLR8 in tuberculosis patients were significantly increased." (PMID 35959378, 2022). "At the same time, comprehensive analysis of SNP allele frequencies in HIV and HIV–tuberculosis samples has not previously been performed, in particular for TLR6 and TLR8 as the most promising markers of the genetic risk of coinfection." (PMID 37606452, 2023). "In support of this hypothesis, the TLRs are upregulated as a group in both melioidosis (TLR1, TLR2, TLR4, TLR5, TLR6, TLR8 and TLR10) and tuberculosis (TLR2, TLR4, TLR5, TLR6, TLR7, TLR8)." (PMID 23383015, 2013).